NEO1 (neogenin 1)
Description:
Multi-functional cell surface receptor regulating cell adhesion in many diverse developmental processes, including neural tube and mammary gland formation, myogenesis and angiogenesis. Receptor for members of the BMP, netrin, and repulsive guidance molecule (RGM) families. Netrin-Neogenin interactions result in a chemoattractive axon guidance response and cell-cell adhesion, the interaction between NEO1/Neogenin and RGMa and RGMb induces a chemorepulsive response.
Synonyms: IGDCC2; NGN; HsT17534; NTN1R2
Tractability: Antibody: its Gene Ontology location is reachable by antibodies, with high confidence; UniProt places it where antibodies can reach, with medium confidence; UniProt predicts a signal peptide or a membrane-spanning region. PROTAC: ubiquitination databases record sites on it; its protein half-life has been measured.
Gene: Protein-coding gene on chromosome 15 (73,051,645 to 73,305,205, forward strand). Ensembl gene ENSG00000067141.
Subcellular location: Cell membrane
Subcellular location (Human Protein Atlas): Nucleoplasm; Plasma membrane; Golgi apparatus
Pathways (Reactome):
Developmental Biology: Myogenesis; Netrin-1 signaling
Gene Ontology:
Molecular function: co-receptor binding; protein binding
Biological process: multicellular organismal-level iron ion homeostasis; axon guidance; cell adhesion; cell-cell adhesion; neuron migration
Cellular component: plasma membrane; plasma membrane protein complex; cell surface; membrane
Genetic constraint (gnomAD): Loss-of-function variants: 57 observed, 143.56 expected, observed/expected ratio (o/e) 0.4, 90% interval 0.32 to 0.5. The upper end of that interval is the gene's LOEUF score, 0.5, which puts it in group 2 of 6, group 1 being the genes least tolerant of losing a copy. Missense variants: 1,513 observed, 1,761.6 expected, observed/expected ratio (o/e) 0.86, 90% interval 0.82 to 0.9. Synonymous variants: 592 observed, 636.48 expected, observed/expected ratio (o/e) 0.93, 90% interval 0.87 to 1.
Homologues: Orthologues: chimpanzee NEO1 (99% identical), macaque NEO1 (98% identical), pig NEO1 (96% identical), dog NEO1 (95% identical), mouse Neo1 (95% identical), rat Neo1 (94% identical), guinea pig NEO1 (94% identical), rabbit NEO1 (86% identical), zebrafish neo1a (69% identical), tropical clawed frog neo1 (69% identical), zebrafish neo1b (62% identical). Paralogues in human: DCC (51% identical), ROBO1 (18% identical), ROBO2 (18% identical), SDK2 (18% identical), SDK1 (18% identical), IGDCC4 (18% identical), CNTN3 (17% identical), CNTN4 (17% identical), ROBO3 (17% identical), PRTG (16% identical), MXRA5 (16% identical), CNTN5 (16% identical), and 24 more.
Diseases named in the same sentence as NEO1 in open-access papers:
NEO1 is named in the same sentence as 67 diseases in open-access papers, as found by Europe PMC text mining. Sharing a sentence is not in itself a finding about the gene and the disease. The quoted sentences say what the papers report.
colorectal cancer (13 papers, 2014 to 2024). A primary or metastatic malignant neoplasm that affects the colon or rectum. "For example, the loss of expression of neogenin-1 in breast cancer and colorectal cancer has already been studied, and it appears that the RGMa/neogenin-1 interaction inhibits cancer growth and migration." (PMID 24930499, 2014). "As examples of DRs relevant to the topic of this review, DCC netrin 1 receptor (DCC, previously named deleted in colorectal carcinoma) and its homologue neogenin (NEO1) are discussed." (PMID 36231134, 2022). "We showed that draxin controls axon guidance through netrin-1 receptors, Deleted in colorectal cancer (Dcc) and Neogenin (Neo1)." (PMID 34899198, 2021). "Especially, all analyses (9 analyses) about colorectal cancer exhibited coincidentally lower NEO1 expression in tumors." (PMID 33088218, 2020). "Neogenin-1 (NEO1) was originally identified as a homologue of the Deleted in Colorectal Cancer (DCC) gene, which acted as a receptor for Netrins and Repulsive Guidance Molecule (RGM) proteins." (PMID 33088218, 2020). "Online databases, Gene Set Enrichment Analysis (GSEA), quantitative real-time PCR and western blotting were used to evaluate NEO1 expression in colorectal cancer tissues." (PMID 33088218, 2020). "Meanwhile, NEO1 also showed lower expression in rectal adenocarcinoma in Gaedcke dataset (fold change = -−2.949, p = 4.24E-24), in colorectal carcinoma in Hong dataset (fold change = -−1.756, p = 9.18E-13) and Skrzypczak dataset (fold change = -−2." (PMID 33088218, 2020). "Furthermore, NEO1 plays a role in tumor progression, angiogenesis, apoptosis and migration in colorectal cancer and neuroblastoma cells." (PMID 39696035, 2024). "It promotes axon path finding and nerve regeneration through its interaction with the canonical receptors deleted in colorectal cancer (Dcc) or the homolog neogenin-1 (Neo1), while it acts as a repulsion molecule through the receptors uncoordinated (Unc5b) and Dcc/Unc in nerve regeneration." (PMID 34576252, 2021). "In mammals, the receptors that interact with secreted netrins include deleted in colorectal cancer (DCC), the analogous neogenin (NEO1) and the uncoordinated 5 homologue (UNC5H) family." (PMID 38546656, 2024). "The mRNA expression of NEO1 was increased (p < 0.05) in HT-29 cells and gene expression levels of UNC5B remained unchanged in both colorectal cancer cell lines." (PMID 36831381, 2023). "Whilst RGM-mediated signaling is specific to NEO1, NET1 can signal via both NEO1 and deleted in colorectal cancer (DCC), a structural homologue of NEO1." (PMID 33740419, 2021). "We showed that draxin genetically interacted with Deleted in colorectal cancer (DCC) and Neogenin (Neo1)." (PMID 26659141, 2015). "Netrin-1 could bind to the receptors deleted in colorectal cancer (DCC), neogenin-1(Neo-1), or uncoordinated (UNC5) and then participate in the formation of various chronic pain conditions." (PMID 35966013, 2022). "NTN-1 exerts chemoattractive or chemorepulsive functions depending on its receptors, including neogenin-1 (NEO-1), deleted in colorectal carcinomas (DCC), A2B receptor (A2BAR), uncoordinated-5 homolog family members (UNC5A, UNC5B, UNC5C, and UNC5D), CD146, and integrin subunits." (PMID 36297056, 2022). "In addition, deleted in colorectal cancer (DCC), instead of neogenin-1(Neo-1) or uncoordinated (UNC5), was proved to be the specific functional receptor of Netrin-1 in regulating visceral hypersensitivity, whose upregulation may result in the most severe symptoms in the prepubertal period." (PMID 35966013, 2022).
gastric cancer (8 papers, 2014 to 2023). A primary or metastatic malignant neoplasm involving the stomach. "NEO1 is also relevant for cell migration in several cancers, including gastric cancer and NB, however, the associated signaling mechanisms have not been elucidated." (PMID 33724150, 2021). "The function of neogenin-1 was also determined by assessment of gain and loss of function of neogenin-1 in gastric cancer cell proliferation and migration." (PMID 24930499, 2014). "For example, neogenin-1 promotes gastric cancer cell proliferation and motility, and an IL-17 polymorphism might be the main risk factor for gastric cancer in China and Japan." (PMID 28881766, 2017). "In addition, we propose further studies for neogenin-1 and its associated pathways to provide them as a proper target for gastric cancer therapy." (PMID 24930499, 2014). "One the other hand, NEO1 was investigated to be overexpressed in gastric cancer and medulloblastoma, promoting cancer cell proliferation and motility." (PMID 33088218, 2020). "The overexpression of NEO1 in gastric cancer increases cell motility, acquiring a migratory phenotype, and its knock-down reduces cell migration in the same cell types." (PMID 28038459, 2017). "In other cell types, such as gastric cancer, NEO1 modulates the effect of endogenous NTN4 on motility." (PMID 28038459, 2017). "It has been reported that overexpression of NEO1 in gastric cancer is involved in cell proliferation and migration." (PMID 26296091, 2015). "Taken together, our results suggest that neogenin-1 increases gastric cancer cell motility, and its expression is highly regulated in gastric cancers through interactions with galectin-3 and HSF-1." (PMID 24930499, 2014). "Neogenin-1 ablation decreased proliferation and migration of gastric cancer cells, whereas its over-expression reversed these effects." (PMID 24930499, 2014). "The expression levels of galectin-3 and neogenin-1 were analyzed in 20 gastric cancer patients obtained from the National Cancer Center of Korea." (PMID 24930499, 2014). "Neogenin-1 over-expression plasmids were transfected into SNU-668 cells, which demonstrate low expression of neogenin-1 in twelve gastric cancer cell lines." (PMID 24930499, 2014). "Taken together, high-expression of neogenin-1 promotes gastric cancer proliferation and motility and its expression is regulated by HSF-1 and galectin-3 interaction." (PMID 24930499, 2014). "Taken together, neogenin-1 appears to regulate ROCK1 activation leading to gastric cancer cell migration and invasion." (PMID 24930499, 2014). "Xenografted analyses using gastric cancer cells displayed statistically significant inhibition of tumor growth by neogenin-1 depletion." (PMID 24930499, 2014). "Neogenin-1 is thought to be up-regulated during gastric cancer development and is involved in gastric cancer growth and metastasis in a ligand-independent manner." (PMID 24930499, 2014). "The cell migration by ablation of neogenin-1 distinctively lessened the migration of 5 of the gastric cancer cells except SNU-216, whereas the ablation of netrin-1 had no significant reduction." (PMID 24930499, 2014). "We investigated the expression of neogenin-1 in 59 cases of gastric cancer tissues and normal tissues of gastric cancer patients." (PMID 24930499, 2014). "In order to further explore how galectin-3 increases neogenin-1 expression in gastric cancer cells, we focused on the transcription factor, heat shock factor 1 (HSF-1), as a major regulator of heat shock protein transcription." (PMID 24930499, 2014). "In our study, the expression of neogenin-1 was relatively high and easily detectable in twelve gastric cancer cell lines." (PMID 24930499, 2014). "In this study, we first determined the expression of neogenin-1 in gastric cancer patients and gastric cancer cells." (PMID 24930499, 2014).
gastric cancer (continued). "Taken together, our results demonstrated that HSF-1 increases gastric cancer cell motility through regulation of neogenin-1 expression, and the transcriptional activation of HSF-1 is regulated by galectin-3." (PMID 24930499, 2014). "In this study, we confirmed for the first time that neogenin-1 is highly expressed in gastric cancer and promotes gastric cancer proliferation and migration." (PMID 24930499, 2014). "To understand how neogenin-1 expression is up-regulated in gastric cancer, we searched for transcription factor binding sites in the neogenin-1 promoter region using a transcription factor binding site prediction program." (PMID 24930499, 2014). "Therefore, we demonstrate herein the effects of neogenin-1 on gastric cancer cell proliferation and migration, as well as the regulation of its expression by HSF-1 and galectin-3 interactions." (PMID 24930499, 2014). "Therefore, we demonstrated here the function and regulatory mechanism of neogenin-1 in gastric cancer." (PMID 24930499, 2014). "Moreover, we also established the parallel protein expression and co-localization of HSF-1 and neogenin-1 in malignant tissues of gastric cancer patients." (PMID 24930499, 2014). "To establish whether neogenin-1 induced gastric cancer cell migration and invasion through ROCK1 activation, we over-expressed neogenin-1 in SNU-668 cells and decreased the expression of ROCK1 by ROCK1 siRNA." (PMID 24930499, 2014). "Moreover, the parallel expression patterns of galectin-3 and neogenin-1, as well as those of HSF-1 and neogenin-1, were detected in the malignant tissues of gastric cancer patients." (PMID 24930499, 2014). "Moreover, only ablation of neogenin-1 reduced gastric cancer cell proliferation and migration, whereas ablation of netrin-1 had little effect." (PMID 24930499, 2014). "Interestingly, galectin-3 interacted with HSF-1 directly, which facilitated nuclear-localization and binding on neogenin-1 promoter to drive its transcription and gastric cancer cell motility." (PMID 24930499, 2014). "Neogenin-1 also appears to regulate gastric cancer cell motility through the activation of ROCK." (PMID 24930499, 2014). "Moreover, NEO1 activates RAC1-PI3K-AKT signaling pathway in human gastric cancer cells." (PMID 32042028, 2020). "Moreover, ROCK1 increases gastric cancer cell migration and invasion, and the inhibition of ROCK1 induces apoptosis in gastric cancer cells, suggesting that neogenin-1 increases the activation of ROCK1 and, in turn, promotes gastric cancer cell survival and motility." (PMID 24930499, 2014). "Because HSF-1 increased neogenin-1 expression, we determined the regulatory effect of HSF-1 on migration of gastric cancer cells." (PMID 24930499, 2014). "Therefore, our results strongly suggest that neogenin-1 was more detected in malignant tissues and its expression was positively correlated with both HSF-1 and galectin-3 in the malignant tissues of gastric cancer patients." (PMID 24930499, 2014). "Our results suppose that the effect of neogenin-1 on the proliferation and migration gastric cancer cells and is independent of its ligand netrin-1." (PMID 24930499, 2014). "Moreover, parallel and high expression of neogenin-1 and galectin-3, as well as neogenin-1 and HSF-1, was detected in human gastric cancer tissue." (PMID 24930499, 2014). "Although the case number of patients was not enough, we found the expression levels of neogenin-1 was higher in diffuse type than intestinal type of gastric cancer tissues." (PMID 24930499, 2014). "Although elevated expression of neogenin-1 has been detected in human gastric cancer tissue, its role in gastric tumorigenesis remains unclear due to the lack of neogenin-1 studies in cancer." (PMID 24930499, 2014).
breast carcinoma (4 papers, 2014 to 2024). "Our results corroborate other studies where loss of Neo1 has been associated with increased rates of cell migration in MDA-MB-231 human breast cancer cells." (PMID 30858446, 2019). "The cleaved NEO1-ICD undergoes a rapid proteasome degradation in breast cancer cell lines and neuronal extracts." (PMID 39454953, 2024). "It was reported that NEO1 expression was down-regulated in glioma and breast cancer and played as a tumor suppressor by inhibiting proliferation and inducing apoptosis." (PMID 33088218, 2020). "Recently, abnormal expression of NEO1 has been demonstrated in some kinds of cancer such as glioma, breast cancer and pancreatic cancer, but little is known about its specific functions." (PMID 33088218, 2020). "For example, low expression of neogenin-1 is seen in breast cancers, colon cancers and glioma, moderate expression in pancreatic cancer and high expression in ESCC compared to the same healthy organs." (PMID 24930499, 2014).
neuroblastoma (4 papers, 2017 to 2024). Neuroblastoma (NB) is the most common solid, extracranial childhood tumor. "Focal Adhesion Kinase (FAK) is a regulator of cell migration that binds to the receptor Neogenin-1 and is upregulated in neuroblastoma." (PMID 33724150, 2021). "Taken together, these data show that Neogenin-1 is a metastasis-promoting protein that associates with FAK, activates integrin β1 and promotes neuroblastoma cell migration." (PMID 33724150, 2021). "Moreover, Neogenin-1, which was detected in all tumor stages and was required for neuroblastoma cell migration, was found in a complex with integrin β1, FAK, and Netrin-1." (PMID 33724150, 2021). "Furthermore, NTN4 was shown to act as a cell adhesion molecule required for the migration induced by Neogenin-1 (NEO1) in SK-N-SH neuroblastoma cells." (PMID 30160193, 2019). "Importantly, Neogenin-1 promoted neuroblastoma metastases in an immunodeficient mouse model." (PMID 33724150, 2021). "To determine the contribution of NEO1 in NB progression, we first evaluated its expression in NB patients (n = 21) by immunohistochemistry on paraffin-embedded samples, categorized according to INRGSS (International Neuroblastoma Risk Group staging system)." (PMID 33724150, 2021). "Here, we show that Netrin-1 ligand binding to Neogenin-1 leads to FAK autophosphorylation and integrin β1 activation in a FAK dependent manner, thus promoting neuroblastoma cell migration." (PMID 33724150, 2021). "As MYCN amplification is associated with NB aggressiveness and poor prognosis (MYCN protein expression as a predictor of neuroblastoma prognosis), we evaluated the relation in between MYCN amplification and NEO1/NTN4 expression." (PMID 28038459, 2017). "Public databases contain extensive information regarding the expression of NEO1 and its ligands Netrin-1 (NTN1) and Netrin-4 (NTN4) in primary neuroblastoma (NB) tumors." (PMID 28038459, 2017).
endothelial dysfunction (3 papers, 2022 to 2024). In vascular diseases, endothelial dysfunction is a systemic pathological state of the endothelium (the inner lining of blood vessels) and can be broadly defined as an imbalance between vasodilating and vasoconstricting substances produced by (or acting on) the endothelium. "Similarly, CREB1 interacts with BAF47 (BRG1-associated factor 47) and recruits BAF47 to the proximal neogenin 1 promoter, leading to neogenin 1 trans-activation that contributes to endothelial dysfunction." (PMID 36186432, 2022). "In conclusion, our data delineate a novel transcriptional mechanism underlying Neo-1 activation in vascular endothelial cells that might contribute to endothelial dysfunction and atherosclerosis." (PMID 35186922, 2022). "Here we investigated the role of neogenin 1 (Neo-1) in oxidized low-density lipoprotein (oxLDL) induced endothelial dysfunction focusing on its transcriptional regulation." (PMID 35186922, 2022). "Next, we decided to extrapolate the finding that Neo-1 might be involved in endothelial dysfunction in a classic animal model in which Apoe−/− mice were fed a Western diet for 8 weeks to develop atherosclerotic lesions." (PMID 35186922, 2022). "In this study, we identify cerebrospinal fluid Neo1 as a biomarker for poor prognosis in SAH patients, linking BBB disruption to endothelial dysfunction mediated by astrocytic Neo1." (PMID 39107268, 2024).
medulloblastoma (3 papers, 2014 to 2020). A malignant, invasive embryonal neoplasm arising from the cerebellum. "Neogenin-1 is present in tissues where active growth takes place, and overexpression of neogenin-1 has been observed in a wide variety of human cancers including those of the breast, pancreas, cervix, colon, medulloblastoma and rectum." (PMID 24930499, 2014). "Furthermore, studies in vitro and patient samples have demonstrated that the interaction between NEO1 and NTN1 is associated with cell migration and invasiveness in medulloblastoma, another pediatric malignancy." (PMID 28038459, 2017). "In addition, NEO1 expression was higher in SK-N-SH, when compared to other cancer cell lines such as DAOY (medulloblastoma), U87 (glioblastoma), and HEK293 cells." (PMID 28038459, 2017). "However, NEO1 knock-down does not reduce cell death and its expression is maintained in several cancer cells, such as NB and medulloblastoma." (PMID 28038459, 2017).
atherosclerosis (2 papers, 2022 to 2025). A disease characterized by the build-up of fatty material and calcium deposition in the arterial wall resulting in partial or complete occlusion of the arterial lumen. "Importantly, Neo-1 inhibition in Apoe−/− mice dampens atherosclerosis." (PMID 35186922, 2022).